PFDN4 (prefoldin subunit 4)
Description:
Binds specifically to cytosolic chaperonin (c-CPN) and transfers target proteins to it. Binds to nascent polypeptide chain and promotes folding in an environment in which there are many competing pathways for nonnative proteins.
Synonyms: PFD4; C-1; C1
Tractability: Small molecule: a structure with a bound ligand is known. PROTAC: ubiquitination databases record sites on it; its protein half-life has been measured.
Gene: Protein-coding gene on chromosome 20 (54,207,817 to 54,228,052, forward strand). Ensembl gene ENSG00000101132.
Subcellular location: Nucleus; Cytoplasm; Mitochondrion
Pathways (Reactome):
Metabolism of proteins: Prefoldin mediated transfer of substrate to CCT/TriC
Gene Ontology:
Molecular function: amyloid-beta binding; protein binding; protein-folding chaperone binding
Biological process: negative regulation of amyloid fibril formation; protein folding
Cellular component: cytoplasm; mitochondrion; nucleus; prefoldin complex; cytosol
Genetic constraint (gnomAD): Loss-of-function variants: 0 observed, 0.52 expected, observed/expected ratio (o/e) 0, 90% interval 0 to 1.83. That is too few expected variants to judge how well the gene tolerates losing a copy. Missense variants: 17 observed, 7.5 expected, observed/expected ratio (o/e) 2.27. Synonymous variants: 4 observed, 2.33 expected, observed/expected ratio (o/e) 1.71, 90% interval 0.69 to 1.94.
Homologues: Orthologues: chimpanzee PFDN4 (100% identical), macaque PFDN4 (100% identical), dog PFDN4 (97% identical), mouse Pfdn4 (97% identical), rat Pfdn4 (95% identical), zebrafish pfdn4 (82% identical), Drosophila melanogaster Pfdn4 (43% identical), Caenorhabditis elegans pfd-4 (37% identical).
Diseases named in the same sentence as PFDN4 in open-access papers:
PFDN4 is named in the same sentence as 16 diseases in open-access papers, as found by Europe PMC text mining. Sharing a sentence is not in itself a finding about the gene and the disease. The quoted sentences say what the papers report.
colorectal cancer (7 papers, 2020 to 2024). A primary or metastatic malignant neoplasm that affects the colon or rectum. "Higher PFDN4 expression was associated with better survival in colorectal cancer patients." (PMID 35111762, 2021). "Moreover, a recent study showed that the upregulation of CYP24A1 and PFDN4 as well as nearby lncRNAs may be used as the potential diagnostic biomarker in colorectal cancer." (PMID 34422647, 2021). "Like CSE1L, increased expression of PFDN4 was reported in various types of cancerous tumors, such as colorectal cancer, hepatocellular carcinoma, gastric cancer, breast cancer, or epithelial ovarian cancer." (PMID 37371576, 2023). "A study has suggested that PFDN4 expression serves to predict the prognosis of colorectal cancer." (PMID 38835051, 2024). "This suggests that in the context of colorectal cancer, PFDN4 functions as a tumor suppressor and may serve as a marker of favorable prognosis." (PMID 35111762, 2021). "For instance, dysregulated PDFN1 expression has been reported to occur in a variety of cancers, including gastric cancer, lung cancer, and colorectal cancer; increased expression of PFDN2 has been found in bladder cancer; and it has been reported that PFDN4 is highly expressed in breast cancer." (PMID 37538116, 2023).
breast carcinoma (4 papers, 2021 to 2024). "Amplification of this chromosome region increased PFDN4 expression, suggesting that PFDN4 is an oncogene that is associated with the development of breast cancer." (PMID 35111762, 2021). "Accumulating evidence shows that the genetic locus of PFDN4 confers potential susceptibility to breast cancer." (PMID 35111762, 2021). "Our research further found that PFDN4 has the ability to antagonize chemotherapy drugs in breast cancer." (PMID 38612711, 2024). "CRISPR knockout of PFDN4 inhibited the growth of 89% of breast cancer cell lines, and the triple-negative cell line exhibited a stronger inhibitory effect than the non-triple-negative cell line." (PMID 38612711, 2024). "In our study, PFDN4 showed higher expression in breast cancer than in normal tissue, and in triple-negative breast cancer than in non-triple-negative breast cancer." (PMID 38612711, 2024). "We further investigated the effects of PFDN4 on chemotherapy resistance to doxorubicin and paclitaxel in breast cancer cell lines." (PMID 38612711, 2024). "We used MCF7 (non-triple-negative) and MDAMB231 (triple-negative) breast cancer cell lines to perform chemotherapy resistance experiments and verify the expression of PFDN4 in MCF7 and MDAMB231 cells." (PMID 38612711, 2024). "We also examined the expression of PFDN4 in breast cancer based on breast cancer subclasses including luminal, HER2 positive and triple-negative group." (PMID 38612711, 2024). "Previous studies have also found that PFDN4 is highly expressed in breast cancer cell lines and identified as an oncogenic gene, this is consistent with our current research." (PMID 38612711, 2024). "Currently, about 5.6% (60/1003 (low expression) + 60 (high expression))) of breast cancer patients are from the PFDN4-high expression group." (PMID 38612711, 2024). "After silencing of PFDN4, the ability of breast cancer cells in cell growth and motility is reduced." (PMID 38612711, 2024). "This study provides insightful evidence for the value of PFDN4 in poor prognosis and chemotherapy resistance in breast cancer patients." (PMID 38612711, 2024). "These disparate results indicate the need for further studies to elucidate the role of PFDN4 in the development of breast cancer." (PMID 35111762, 2021). "Therefore, we suggest that breast cancer patients with high PFDN4 expression should receive tamoxifen treatment." (PMID 38612711, 2024). "In the future, we will further explore how PFDN4 regulates the mitotic spindle in breast cancer." (PMID 38612711, 2024). "This study aimed to investigate the role of PFDN4 in chemotherapy resistance in breast cancer." (PMID 38612711, 2024). "Doxorubicin, paclitaxel and cyclophosphamide do not improve survival in breast cancer patients with high PFDN4 expression." (PMID 38612711, 2024).
gastric cancer (4 papers, 2021 to 2024). A primary or metastatic malignant neoplasm involving the stomach. "The silencing of TWIST increased PFDN4 gene expression levels in gastric cancer cell lines, indicating that PFDN4 might be related to gastric cancer." (PMID 35111762, 2021). "The expression of PFDN4 is regulated by TWIST transcription factor, which plays an important role in the tumorigenesis and metastasis of gastric cancer." (PMID 35111762, 2021).
prostate carcinoma (2 papers, 2022 to 2025). A carcinoma that arises from epithelial cells of the prostate gland. "PFDN4, when combined with SHC4 and CHORDC1, regulates extracellular vesicle secretion in prostate cancer." (PMID 36438659, 2022).
breast invasive carcinoma (1 paper, 2024). "The results show that high expression of PFDN4 was significantly associated with survival rate (p = 0.0235) in breast invasive carcinoma." (PMID 38612711, 2024). "The results showed that high expression of PFDN4 with doxorubicin (p = 0.0003701), paclitaxel (p = 0.001294) and cyclophosphamide (p = 0.003080) was significantly associated with survival rate in breast invasive carcinoma, but the other drugs were not." (PMID 38612711, 2024). "The disease-specific prognostic value of PFDN4 (PFDN4 uses median to differentiate between high and low expression) with drug including doxorubicin, paclitaxel, cyclophosphamide, tamoxifen, anastrazole and docetaxel was determined using Kaplan–Meier analysis in breast invasive carcinoma." (PMID 38612711, 2024).
cervix cancer (1 paper, 2015). "Genes PFDN4, CASP1, PLCE1, ICOSLG, GADD45G, SMARCA2, and TSPO are located in different chromosomes, and there are reports for changes in each one of these chromosomes in cervix cancer, for examples the reader is refer to:." (PMID 26388997, 2015).
liver cancer (1 paper, 2022). An epithelial or non-epithelial malignant neoplasm that arises from the liver. "Higher expression of PFDN1 (HR = 1.49, 95% CI: 1.05–2.10, p = 0.025), PFDN2 (HR = 1.49, 95% CI: 1.05–2.11, p = 0.024), VBP1 (HR = 1.47, 95% CI: 1.03–2.08, p = 0.031), and PFDN4 (HR = 1.78, 95% CI: 1.25–2.53, p = 0.001) was significantly associated with shorter OS of liver cancer patients." (PMID 36438659, 2022).
seminoma (1 paper, 2023). A radiosensitive malignant germ cell tumor found in the testis (especially undescended), and extragonadal sites (anterior mediastinum and pineal gland). "In this regard, CSE1L and PFDN4 could be novel, previously unrecognized cancer-testis antigens, which was partially supported in the case of CSE1L and its role in maintaining cell proliferation and division in seminomas." (PMID 37371576, 2023).
triple-negative breast carcinoma (1 paper, 2024). An invasive breast carcinoma which is negative for expression of estrogen receptor (ER), progesterone receptor (PR), and human epidermal growth factor receptor 2 (HER2). "In our study, we present evidence that PFDN4 overexpression is associated with a higher incidence of chemoresistance in triple-negative breast cancer than in non-triple-negative breast cancer, and is also a prognostic factor for poor prognosis in patients receiving chemotherapy." (PMID 38612711, 2024). "The results showed that silencing PFDN4 has a greater ability to inhibit cell growth in triple-negative compared to non-triple-negative breast cancer cell lines (p = 0.039)." (PMID 38612711, 2024). "We also used CRISPR knockout screens of the PFDN4 system to analyze cell growth in 12 non-triple-negative and 18 triple-negative breast cancer cell lines." (PMID 38612711, 2024).
cancer (8 papers, 2011 to 2024). A tumor composed of atypical neoplastic, often pleomorphic cells that invade other tissues. "Furthermore, empirical evidence has supported that PFDN4 may be associated with the progression of cancer progressions." (PMID 38835051, 2024). "Unlike in somatic/cancer cells, we localized PFDN4 in the extracellular space of the apical ridge of the sperm head in non-capacitated spermatozoa, which became more available for immunolabelling after sperm IVC capacitation." (PMID 37371576, 2023).
tumor (4 papers, 2021 to 2025). "PFDN4 might promote tumor progression through multiple pathways." (PMID 36438659, 2022).
infection (1 paper, 2025). The state of being infected such as from the introduction of a foreign agent such as serum, vaccine, antigenic substance or organism. "Surprisingly, knockout of either PFDN3 or PFDN4 led to an increase in intracellular viral RNA levels of bovine RV UK strain at 48 and 72 h post-infection (hpi)." (PMID 40883306, 2025).
PFDN4 also shares sentences with these, for which no sentence is quoted: bladder cancer (1 paper); colorectal tumor (1); hepatocellular carcinoma (1); lung carcinoma (1).